JMJD1C (jumonji domain containing 1C)
Diseases named in the same sentence as JMJD1C in open-access papers (continued):
Sharing a sentence is not in itself a finding about the gene and the disease.
glioma (3 papers, 2021 to 2023). A benign or malignant brain and spinal cord tumor that arises from glial cells (astrocytes, oligodendrocytes, ependymal cells). "Induction of miR-302a in glioma cells by histone demethylase Jumonji domain-containing 1C (JMJD1C) promotes M1 macrophage polarization, which is associated with enhanced antitumor effects in gliomas." (PMID 37345170, 2023). "According to the bioinformatics analysis results, analysis of JMJD1C expression in glioma samples and normal samples collected by TCGA and GTEX using the GEPIA database suggested a decline of JMJD1C expression in glioma samples." (PMID 34586733, 2021). "JMJD1C promoted M1 macrophage polarization and suppressed the growth of glioma xenografts through the miR‐302a/METTL3/SOCS2 axis both in vivo and in vitro." (PMID 34586733, 2021). "We initially assessed JMJD1C expression in glioma tissues and cells using the assays of RT‐qPCR and immunohistochemistry." (PMID 34586733, 2021). "In conclusion, JMJD1C promotes M1 macrophage polarization and inhibits glioma development through the miR‐302a/METTL3/SOCS2 axis." (PMID 34586733, 2021). "Jumonji domain containing 1C (JMJD1C) is a H3K9 demethylase which participates in the progression of various tumors, but its specific function and underlying mechanism in glioma development remain undefined, which is the purpose of our work." (PMID 34586733, 2021). "Our findings subsequently revealed that JMJD1C promoted M1 macrophage polarization to inhibit glioma progression both in vivo and in vitro." (PMID 34586733, 2021). "As reflected by RT‐qPCR and IHC, there was poor expression of JMJD1C in glioma tumor tissues as compared to adjacent normal tissues." (PMID 34586733, 2021). "Nevertheless, future studies are warranted to further explore the possibilities of using JMJD1C as a biomarker for glioma prognosis and treatment." (PMID 34586733, 2021). "The evidence collected in this study suggest that JMJD1C expression is decreased in glioma, to an extent correlating with the immune response." (PMID 34586733, 2021). "Our results indicate that JMJD1C enhances M1 macrophage polarization to inhibit the onset of glioma, which brings a new insight for the contributions of JMJD1C to the pathobiology of glioma." (PMID 34586733, 2021). "Based on previous literature, we speculated that JMJD1C may affect glioma cell proliferation by regulating miR‐302a." (PMID 34586733, 2021). "In conclusion, JMJD1C could enhance M1 macrophage polarization to inhibit the onset of glioma, bringing a new insight into the contribution of JMJD1C to the pathobiology of glioma, with possible implications for targeted therapeutic method." (PMID 34586733, 2021). "First, the expression profiles of JMJD1C in glioma tumor tissues and cell lines were identified." (PMID 34586733, 2021). "However, the current study provides evidence that JMJD1C plays a tumor‐inhibiting role in glioma by upregulating miR‐302a and further affecting the METTL3/SOCS2‐mediated polarization of M1 macrophages." (PMID 34586733, 2021). "Thus, we can infer that JMJD1C was also involved in the inflammatory response in the glioma model." (PMID 34586733, 2021). "Specifically, JMJD1C promotes H3K9 demethylation at miR-302a promoter regions and increases its expression in glioma cells." (PMID 37345170, 2023). "The cell proliferation of LN‐229 and U251 cells stably overexpressing JMJD1C was screened by EdU staining and CCK‐8 assay, which showed that overexpression of JMJD1C exerted functions on glioma cell proliferation in vitro." (PMID 34586733, 2021). "The role of histone demethylase JMJD1C in glioma has not been comprehensively investigated in previous work." (PMID 34586733, 2021). "The data shown in our study indicate that overexpressed JMJD1C increases the expression of M1 markers (IL‐1β, TNF, CXCL9, IL‐23, ROS1, IL‐12a, and IL‐12b) both in the glioma mouse models and in the CD14+ monocytes co‐cultured with glioma cells." (PMID 34586733, 2021).
Insulin resistance (3 papers, 2020 to 2024). Increased resistance towards insulin, that is, diminished effectiveness of insulin in reducing blood glucose levels. "In addition, six loci were linked to insulin resistance, type 2 diabetes, or reduction in HbA1c levels in type 2 diabetes (APOB, HPR, TM6SF2, KSR2, JMJD1C, and SLCO1B1)." (PMID 38532495, 2024). "Consequently, JMJD1C promotes lipogenesis in vivo to increase hepatic and plasma triglyceride levels, showing its role in metabolic adaption for activation of the lipogenic program in response to feeding/insulin, and its contribution to development of hepatosteatosis resulting in insulin resistance." (PMID 32034158, 2020). "Over-expression of JMJD1C in the liver increases DNL, whereas liver-specific deletion of Jmjd1c protects mice from diet-induced hepatic steatosis and insulin resistance." (PMID 33193730, 2020).
ovarian carcinoma (3 papers, 2011 to 2025). A malignant neoplasm originating from the surface ovarian epithelium. "According to public databases (TCGA), we inferred that high expression of either JMJD1B or JMJD1C indicates poor prognosis in ovarian cancer patients, corroborating their pro-tumorigenic function in ovarian cancer." (PMID 39915607, 2025). "The RPL10L gene is related to ovarian cancer and JMJD1C plays an essential role in embryogenesis and carcinogenesis." (PMID 21533145, 2011).
type 2 diabetes (3 papers, 2017 to 2024). "We used two separate genetic instruments comprising of variants from JMJD1C and SHBG regions and conducted a two-sample Mendelian randomization for type II diabetes (T2D), gout, rheumatoid arthritis (RA), schizophrenia, bipolar disorder, Alzheimer’s disease and depression." (PMID 32610558, 2020).
acute leukemia (2 papers, 2021 to 2023). A clonal (malignant) hematopoietic disorder with an acute onset, affecting the bone marrow and the peripheral blood. "Recently, we have reported the identification of JMJD1C inhibitors that preferentially kill MLL rearranged acute leukemia cells." (PMID 33289299, 2021). "Recently, we reported the identification of inhibitors of the histone lysine demethylase JMJD1C that preferentially kill MLL rearranged acute leukemia cells." (PMID 33289299, 2021).
autism (2 papers, 2013 to 2014). Persistent deficits in social interaction and communication and interaction as well as a markedly restricted repertoire of activity and interest as well as repetitive patterns of behavior. "Although mutations in the JMJD1C gene are linked to the development of autism, this relationship is not fully understood as the histone substrate for this enzyme has not yet been identified." (PMID 24735454, 2014). "JMJD1C has been implicated in the pathophysiology of autism." (PMID 24348429, 2013).
esophageal squamous cell carcinoma (2 papers, 2021). Esophageal squamous cell carcinoma (ESCC) is a type of esophageal carcinoma (EC) that can affect any part of the esophagus, but is usually located in the upper or middle third. "Moreover, knockdown of circ_0006168 or JMJD1C plays a crucial role in inhibiting cell proliferation, invasion, and migration and promoting apoptosis, which accelerates the taxol sensitivity of Esophageal squamous cell carcinoma (ESCC) in vitro." (PMID 35070998, 2021).
Hepatic steatosis (2 papers, 2016 to 2020). Steatosis is a term used to denote lipid accumulation within hepatocytes. "In a mouse model, it was noted that VEGF promotes proliferation of hepatocytes through reestablishment of liver sinusoids by proliferation of sinusoidal endothelial cells; thus VEGF may mediate the genetic association observed between JMJD1C variants and hepatic steatosis." (PMID 26910538, 2016).
infertile (2 papers, 2017 to 2022). "Here, we report an in-depth analysis of the association between two JMJD1C SNPs (rs7910927 and rs10822184) and male reproductive parameters in several well-characterized Danish cohorts of peri-pubertal boys, young men from the general population, and fertile and infertile men." (PMID 29222425, 2017). "JMJD1C, a member of the Jumonji-domain containing histone demethylases protein family, has been associated with levels of sex-hormone binding globulin (SHBG) and testosterone in men, and knock-out rodent models show age-dependent infertility." (PMID 29222425, 2017).
male infertility (2 papers, 2016 to 2021). The inability of the male to effect fertilization of an ovum after a specified period of unprotected intercourse. "The loss of JMJD1C also results in a progressive reduction of SSCs/SPCs and male infertility." (PMID 34113620, 2021).
myocardial infarction (2 papers, 2019 to 2023). Gross necrosis of the myocardium, as a result of interruption of the blood supply to the area, as in coronary thrombosis. "In the validation study, genetically predicted testosterone (based on JMJD1C gene region variants) was positively associated with myocardial infarction (1.37, 1.03 to 1.82)." (PMID 30842065, 2019).
Obesity (2 papers, 2020 to 2021). Accumulation of substantial excess body fat. "On the other hand, genes up-regulated with pregravid obesity enriched to GO terms associated with transcriptional regulation (JMJD1C, CHD1, HIF1A, TCF25, and KLF6)." (PMID 33912153, 2021). "Both WT and JMJD1C-LKO mice on HFD showed a typical obesity phenotype with higher WAT mass." (PMID 32034158, 2020). "We next subjected JMJD1C-LKO mice to high-fat diet (HFD) to test whether Jmjd1c affects diet-induced obesity." (PMID 32034158, 2020). "In contrast, JMJD1C-LKO mice on HFD remained insulin-sensitive, protected from diet-induced obesity-related IR, even when these mice still manifested higher WAT mass." (PMID 32034158, 2020).
prostate carcinoma (2 papers, 2018 to 2021). A carcinoma that arises from epithelial cells of the prostate gland. "JMJD1C, a DNA repair factor, plays multiple important roles in prostate cancer progression." (PMID 33450964, 2021). "Notably variants in the JMJD1C associated with testosterone in older men at increased risk of prostate cancer did not replicate in younger, healthy Chinese men (mean age 37.4 years)." (PMID 29804699, 2018).
anemia (1 paper, 2022). A reduction in the number of red blood cells, the amount of hemoglobin, and/or the volume of packed red blood cells. "The JMJD1C knockout in zebrafish and mice leads to the ablation of megakaryocyte–erythroid lineage anemia." (PMID 36429088, 2022).
breast NETs (1 paper, 2022). "Likewise, JMJD1C, a histone demethylase associated with epigenetic regulation, harboured pathogenetic or unknown variants in 11% of our breast NETs and only 2% in IDCs." (PMID 36085291, 2022).
central obesity (1 paper, 2024). "Lipid synthesis-associated protein FABP5 was identified as a specific interacting protein of JMJD1C and binds to the jumonji domain of JMJD1C, suggesting its potential role in GSD and central obesity (JMJD1C-regulated lipid synthesis)." (PMID 38529389, 2024).
congenital heart disease (1 paper, 2022). A heart disease that is present at birth. "Rare deleterious single-nucleotide variations in JMJD1C have previously been linked to conotruncal type of congenital heart diseases commonly seen in individuals with 22q11·2 deletion or DiGeorge syndrome." (PMID 34968759, 2022).
endometriosis (1 paper, 2025). The growth of functional endometrial tissue in anatomic sites outside the uterine body. "Endometriosis-associated SNP-SNPinter models include 7 SNPs from 9 analyzed loci, such as rs17496332 (A > G) PRMT6, rs780093 (C > T) GCKR, rs10454142 (T > C) PPP1R21, rs3779195 (T > A) BAIAP2L1, rs440837 (A > G) ZBTB10, rs7910927 (G > T) JMJD1C, and rs8023580 (T > C) NR2F2." (PMID 41373783, 2025).
gallstones (1 paper, 2018). Solid crystalline precipitates in the biliary tract, usually formed in the gallbladder, resulting in the condition of cholelithiasis. "Six of the novel gallstone associated variants, or highly correlated variants (r2 > 0.8), have been reported to associate with blood cholesterol levels (in HNF4A, HNF1A, FUT2, FADS2, MARCH8, and JMJD1C)." (PMID 30504769, 2018).
Glucose intolerance (1 paper, 2020). Glucose intolerance (GI) can be defined as dysglycemia that comprises both prediabetes and diabetes. "In contrast, GTT and ITT showed significantly lower glucose levels in JMJD1C-LKO mice, compared to the WT and were similar to when on chow diet, demonstrating that Jmjd1c ablation prevented glucose intolerance and IR from high-CHO feeding." (PMID 32034158, 2020).
gout (1 paper, 2020). A condition characterized by painful swelling of the joints, which is caused by deposition of urate crystals. "For the JMJD1C locus, one unit increase in log transformed testosterone was significantly associated with RA (OR = 1.69, p = 0.02), gout (OR = 0.469, p = 0.001) and T2D (OR = 0.769, p = 0.048)." (PMID 32610558, 2020). "The results of the Mendelian randomization or the JMJD1C locus showed that genetically predicted testosterone was negatively associated with gout (estimate = −0.757, 95% CI = −1.189, −0.324, p = 0.001) and T2D (estimate = −0.262, 95% CI = −0.522, −0.002, p = 0.048)." (PMID 32610558, 2020).
male pattern baldness (1 paper, 2018). "We assessed genetic associations of variants in two gene regions (SHBG and JMJD1C) with several cardiovascular risk factors (lipids, adiponectin, blood pressure, anthropometric traits) plus male pattern baldness, including control outcomes and potential mediators." (PMID 29804699, 2018).
mental disorder (1 paper, 2016). A disease that has its basis in the disruption of mental process. "However, recent progress in the genetic analysis of human diseases noted possible causal relationships between Jmjd1C mutations and mental disorders as well as relationships with various cancers." (PMID 27649575, 2016). "Further detailed investigations to clarify the partners and targets of JMJD1C functions in each cell lineage will provide important clues to understanding the action mechanism of the JMJD1C-dependent regulatory network and to develop novel therapeutic targets for cancers and mental disorders." (PMID 27649575, 2016).
papillary thyroid cancer (1 paper, 2022). "Finally, we investigated the expression levels of the common mutated genes (JMJD1C, MUC16, PDZD2, RYR1, and SLA) in papillary thyroid cancer cell lines (K1, TPC-1 and BCPAP) compared to an immortalized normal thyroid epithelial cell line (Nthy-ori 3-1) by qRT-PCR." (PMID 35996174, 2022).
pulmonary hypertension (1 paper, 2023). Increased pressure within the pulmonary circulation due to lung or heart disorder. "In this study, we found that JMJD1C expression was upregulated in mice exposed to hypoxia, and JMJD1C knockdown attenuated the development of pulmonary hypertension." (PMID 36934091, 2023).
Rett syndrome (1 paper, 2022). A severe neurodevelopmental disorder affecting the central nervous system. "JMJD1C encodes a histone demethylase, and mutations in this gene are associated with Rett Syndrome, a congenital neurological disorder." (PMID 34968759, 2022).
Right ventricular hypertrophy (1 paper, 2023). In this case the right ventricle is more muscular than normal, causing a characteristic boot-shaped (coeur-en-sabot) appearance as seen on anterior- posterior chest x-rays. "Taken together, these results suggest that JMJD1C contributes to the development of right ventricular hypertrophy and pulmonary arterial remodeling in response to hypoxia exposure." (PMID 36934091, 2023). "Right ventricular hypertrophy and pulmonary arterial wall thickening in mice exposed to hypoxia were attenuated by JMJD1C inhibition." (PMID 36934091, 2023). "In this study, we demonstrate that high JMJD1C expression promotes pulmonary arterial vascular remodeling and right ventricular hypertrophy in mice exposed to hypoxia." (PMID 36934091, 2023).
Thrombocytopenia (1 paper, 2022). A reduction in the number of circulating thrombocytes. "We first used the cell line models, cord blood cells, and clinical thrombocytopenia samples to study the expression of JMJD1C in megakaryocytopoiesis." (PMID 36429088, 2022). "Here, we used megakaryopoiesis cell lines, cord blood cells, and thrombocytopenia samples to explore the role of JMJD1C in megakaryopoiesis." (PMID 36429088, 2022). "Here, we used cell line models, cord blood cells, and thrombocytopenia samples, to detect the JMJD1C expression." (PMID 36429088, 2022). "JMJD1C mRNA was relatively lower in thrombocytopenia patients, compared to the normal controls (mean 2.049 vs. 1.184)." (PMID 36429088, 2022). "We collected peripheral blood mononuclear cells from normal controls and thrombocytopenia patients and measured the expression of JMJD1C." (PMID 36429088, 2022). "We first show the JMJD1C expression difference in the PMA-induced cell line models, the thrombopoietin (TPO)-induced megakaryocyte differentiation of the cord blood cells, and also the thrombocytopenia patients, compared to the normal controls." (PMID 36429088, 2022).
Thromboembolism (1 paper, 2019). The formation of a blood clot inside a blood vessel that subsequently travels through the blood stream from the site where it formed to another location in the body, generally leading to vascular occlusion at the distant site. "We found that when using variants in the JMJD1C gene region, genetically predicted serum testosterone was positively associated with thromboembolism in the UK Biobank." (PMID 30842065, 2019).
thyroid cancer (1 paper, 2022). "We found that the high impact mutations in JMJD1C, SLA, PDZD2, identified from in-silico analysis in PTC samples, are missing in the thyroid cancer cell lines analyzed, thus suggesting that the altered expression of these genes is due to other regulative biological mechanisms." (PMID 35996174, 2022). "The analysis showed that the gene expression level of JMJD1C, MUC16 and SLA were statistically down-regulated while the gene expression level of PDZD2 and RYR1 were up-regulated in thyroid cancer with respect to normal thyroid tissues." (PMID 35996174, 2022).
thyroid tumor (1 paper, 2022). A benign or malignant neoplasm affecting the thyroid gland. "We aimed to evaluate the common mutated genes (JMJD1C, MALAT1, MUC16, PDZD2, PKHD1, RYR1, SLA and TTN) between thyroid tumor and normal samples." (PMID 35996174, 2022).
unstable angina (1 paper, 2020). "In this study, we examined the associations between polymorphisms in GP6 (rs1671152), PEAR1A (rs12566888), MRVI1 (rs7940646), PIK3CG (rs342286), JMJD1C (rs10761741), and SHH (rs2363910) and unstable angina." (PMID 33076381, 2020). "The results of this study suggest a lack of association between GP6 (rs1671152), PEAR1A (rs12566888), MRVI1 (rs7940646), PIK3CG (rs342286), JMJD1C (rs10761741), SHH (rs2363910), and unstable angina." (PMID 33076381, 2020).